MSX1 (msh homeobox 1)
Diseases named in the same sentence as MSX1 in open-access papers (continued):
Sharing a sentence is not in itself a finding about the gene and the disease.
tooth agenesis (continued). "Congenital tooth agenesis is caused by mutations in the MSX1, PAX9, WNT10A, or AXIN2 genes." (PMID 26030286, 2015). "Taken together, besides the genetic background, our present clinical and genetic observations clearly showed that epigenetic or environmental factors also affect the phenotype of missing tooth patterns in a patient with nonsyndromic tooth agenesis caused by MSX1 haploinsufficiency." (PMID 26030286, 2015). "We have found in our current study that MSX1 mutations in a familial-form of oligodontia (in a proband with a 13 tooth-loss including four third molars), and in an apparently sporadic-form of hypodontia (a proband with a nine tooth-loss including four third molars)." (PMID 25101640, 2014). "Second bicuspids and third molars are frequently involved in MSX1-associated tooth agenesis." (PMID 23227268, 2012). "Therefore, it is hypothesized that polymorphisms in PAX9 and MSX1 may increase the risk of tooth agenesis in individuals." (PMID 40226363, 2025). "Furthermore, mutations in MSX1 were associated with tooth agenesis and orofacial clefting in human." (PMID 30704473, 2019). "This implies that loss of function in a single allelic MSX1 could result in a much milder tooth phenotype and that particular genetic backgrounds may have influenced the number of missing teeth in all of the tooth agenesis cases that have been reported previously." (PMID 26030286, 2015). "Taken together with the genetic findings, this case supports the involvement of MSX1 in congenital tooth agenesis and broadens the reported phenotypic presentation of MSX1-related tooth agenesis." (PMID 41927542, 2026). "Mutations in genes such as PAX9, MSX1, and BMP4 have been associated with tooth agenesis, abnormal dental development, and ectopic eruption patterns." (PMID 40625479, 2025). "The genetic basis of tooth agenesis is well-established, with several genes identified as controlling factors, namely MSX1, PAX9, AXIN2, EDA, IRF6, FGFR1, and WNT10A." (PMID 40040530, 2025). "In this study, we initially examined the genotype distribution and allele frequency of SNPs of the MSX1, PAX9, and AXIN2 genes that were previously identified in GWAS as being associated with hypodontia susceptibility." (PMID 39183201, 2024). "Tooth agenesis is associated with several genes; however, non-syndromic human tooth agenesis has been associated with mutations in AXIN2, EDA, PAX9, MSX1, and PAX9." (PMID 39156431, 2024). "Msh homeobox 1 (MSX1) and paired box protein 9 (PAX9) were discovered as the first and second genes associated with tooth agenesis." (PMID 38021739, 2023). "Among them, the transcription factors, paired box gene 9 (PAX9) and Msh Homeobox 1 (MSX1), have emerged as genes likely to be responsible for isolated/non-syndromic hypodontia and oligodontia." (PMID 35273362, 2022). "Mutations in PAX9, MSX1, WNT10A, and AXIN2 genes are most commonly associated with non-syndromic tooth agenesis in the literature." (PMID 36561383, 2022). "In this study, we investigated four candidate genes MSX1, PAX9, AXIN2, and WNT10A in an Iranian family with hereditary non-syndromic tooth agenesis to find the variants responsible for tooth agenesis." (PMID 36561383, 2022). "The aim of the present study was to identify the mutations in the candidate genes, PAX9, MSX1 and WNT10A, responsible for tooth agenesis in 4 Iranian families with hereditary pattern of non-syndromic tooth agenesis." (PMID 33014315, 2020). "Among several genes involved in tooth development, mutations in MSX1, PAX9, AXIN2, WNT10A, EDA and KDF1 have been reported to play a role in tooth agenesis 6–13." (PMID 33014315, 2020). "Mutations of several genes such as PAX9, MSX1, AXIN2, KDF1 and WNT10A have been reported which are associated with non-syndromic tooth agenesis." (PMID 33014315, 2020). "Research has identified an association between mutations in MSX1, PAX9, EDA, AXIN2, WNT10A, WNT10B and LRP6 and human tooth agenesis." (PMID 31914153, 2020).
tooth agenesis (continued). "Most often reported genes associated with nonsyndromic tooth agenesis are PAX9, MSX1, EDA, and AXIN2." (PMID 31781599, 2019). "Most often reported genes associated with the familial form of the nonsyndromic tooth agenesis are paired box gene 9 (PAX9), Msh homeobox 1 (MSX1), ectodysplasin A (EDA), and axis inhibitor protein 2 (AXIN2)." (PMID 31781599, 2019). "A significant association was observed between the heterozygous genotype of the MSX1 rs8670 SNP and its 2.54 times higher risk of developing NSH; meanwhile, the risk of developing hypodontia is 5.53 times for the homozygous variant genotype." (PMID 31781599, 2019). "Some of the studies reported MSX1 and PAX9 mutations in molar and bicuspid agenesis, and the PAX9 gene was positively associated with hypodontia susceptibility." (PMID 31781599, 2019). "We identified a novel frameshift mutation of the highly conserved C-terminal domain of MSX1, known as Msx homology domain 6 (MH6), in a Japanese family with non-syndromic tooth agenesis." (PMID 27917906, 2016). "Since MSX1 and PAX9 are linked to the pathogenesis of nonsyndromic tooth agenesis, we performed detailed mutational analysis of these two genes sampled from Japanese patients." (PMID 25101640, 2014). "We analyzed the MSX1 and PAX9 nucleotide sequences of 19 Japanese tooth agenesis patients, and thereby identified two novel mutations in the MSX1 gene." (PMID 25101640, 2014). "In contrast to MSX1, both missense and frame-shift mutations in PAX9 have been associated with hypodontia." (PMID 24121910, 2014). "Causative genes, MSX1 and PAX9, can be proposed by the observation that mutations of these genes cause familial and sporadic forms of selective tooth agenesis." (PMID 24319603, 2013). "Importantly, mutations in PAX9 and MSX1 have been strongly linked to tooth agenesis, particularly hypodontia and oligodontia; PAX9 is linked to posterior tooth agenesis, while MSX1 is more frequently associated with anterior tooth agenesis." (PMID 40982116, 2025). "Oligodontia and hypodontia have been linked to mutation of PAX9 and MSX1 gene." (PMID 39156431, 2024). "Variants affecting the homeodomain (HD) of MSX1 typically cause tooth agenesis, with or without additional phenotypes." (PMID 38523193, 2024). "However, the phenotypes of non-syndromic tooth agenesis caused by variants in PAX9 and MSX1 are different." (PMID 39767847, 2024). "In recent literature the influence of MSX1 in tooth agenesis is controversial." (PMID 38523193, 2024). "In humans, variants in the MSX1 gene are associated with non-syndromic tooth agenesis (OMIM #106600), non-syndromic cleft lip, with or without cleft palate (OMIM #608874), Witkop syndrome (OMIM #189500), and Wolf-Hirschhorn syndrome (OMIM #194190)." (PMID 39767847, 2024). "They investigated 31 MSX1 variants causing tooth agenesis with or without other phenotypes, as well as different syndromes." (PMID 36672972, 2023). "We observed links between several causative genes, including Msx1 and USAG-1, with the recovery of congenital tooth agenesis but not cleft palate in Msx1-deficient mice." (PMID 33579703, 2021). "We investigated the etiology of human tooth agenesis by exome analysis in Japanese patients, and found a previously undescribed heterozygous deletion (NM_002448.3(MSX1_v001):c.433_449del) in the first exon of the MSX1 gene." (PMID 34285200, 2021). "Few other genes and mutation is the more predominant factor which might be contributing to hypodontia compared to MSX1." (PMID 33708320, 2020). "Therefore, it seems to be likely that the detected MSX1 haploinsufficiency plays a role in the occurrence of the cleft palate and hypodontia phenotype in the affected piglets." (PMID 31068123, 2019). "In humans, MSX1 defects have been reported to cause sporadic or familial nonsyndromic tooth agenesis." (PMID 30134957, 2018).
tooth agenesis (continued). "Among these genes, PAX9 (paired box gene 9), MSX1 (muscle segment homeobox 1), AXIN2 (axis inhibition protein 2), and EDA (ectodysplasin A) are the most frequently reported genes associated with nonsyndromic hypodontia." (PMID 28401166, 2017). "When considering isolated cases or the nonsyndromic form, many studies have investigated the correlation between tooth agenesis and genetic mutations present in individuals belonging to one and the same family, attributing the mutations to genes PAX9, MSX1, AXIN2, and EDA." (PMID 25215247, 2014). "Mutations in MSX1 are also associated with oro-facial clefting, with and without hypodontia and with Witkop syndrome." (PMID 19913215, 2009). "Moreover, we summarized and analysed the MSX1-related tooth agenesis positions and found that the type and variant locus were not related to the severity of tooth loss." (PMID 33419968, 2021). "In the present study, MSX1 gene is mutated in familial hypodontia; however, the mutation of MSX1 alone might not cause phenotype change to the patient." (PMID 33708320, 2020). "Interestingly, heterozygous variants of MSX1 (OMIM 106600) have been identified in human patients with various rare autosomal dominant conditions characterized by tooth agenesis with or without orofacial cleft." (PMID 31068123, 2019). "However, the mechanism of how MSX1 mutation results in tooth agenesis is still not fully understood." (PMID 30134957, 2018). "However, there is no clear correlation between the severity of the hypodontia and the severity of the effect on the MSX1 protein caused by the identified missense mutations." (PMID 24121910, 2014). "To date, mutations in AXIN2 (axis inhibition protein 2), EDA (ectodysplasin A), MSX1 (msh homeobox 1), PAX9 (paired box 9) and WNT10A (wingless-type MMTV integration site family, member 10a) have been demonstrated to be associated with non-syndromic tooth agenesis." (PMID 24278334, 2013). "Several genes, including MSX1, PAX9, AXIN2, WNT10A and EDA have been reported to involve in tooth agenesis." (PMID 33014315, 2020). "The nature of this association would be better determined by genetic investigations in humans, taking into consideration the different pathways of PAX9, MSX1, and AXIN2 acting on both hypodontia and delayed dental development." (PMID 26462655, 2016). "In addition, a nonstop mutation of MSX1 has been shown to be a cause of tooth agenesis." (PMID 26030286, 2015). "PAX9, MSX1, AXIN2, WNT10A and EDA have been experimentally established for congenitally missing teeth like hypodontia and oligodontia." (PMID 25203534, 2014). "As PAX9, MSX1, and AXIN2 are most frequently associated with non-syndromic hypodontia, we studied these specific genes." (PMID 39183201, 2024). "In this family, Sanger sequencing detected no mutations in PAX9, AXIN2, MSX1, or WNT10A, which were previously reported as gene candidates for isolated tooth agenesis." (PMID 34545288, 2021). "In addition, mutations in MSX1 have also been reported in families with dominantly inherited congenital absence of several permanent teeth, called oligodontia or hypodontia, with or without cleft lip and/or palate, no oligodontia or hypodontia was observed in the proband." (PMID 29134539, 2018). "Candidate genes, such as PAX9, MSX1, AXIN2, and EDA, are related to etiology of tooth agenesis." (PMID 25215247, 2014). "In the present study, we present the analysis of the phenotype and the genotype of six families affected by severe tooth agenesis associated with other dental anomalies and systemic entities, in which mutations of genes PAX9 and MSX1 were not identified." (PMID 24316698, 2014). "Coding mutations within MSX1 and PAX9 have been identified in patients with either nonsyndromic or syndromic forms of tooth agenesis." (PMID 25101640, 2014).
tooth agenesis (continued). "The molecular mechanism of human tooth agenesis mediated by MSX1 mutation is however independent of PAX9, since most MSX1 mutations related to oligodontia can potentiate PAX9-induced Bmp4-promoter activation." (PMID 25101640, 2014). "In another pedigree investigated in this study, we identified one sporadic hypodontia case with a unilateral cleft lip and palate, but no MSX1 or PAX9 gene variations were detected." (PMID 25101640, 2014). "MSX1, PAX9, AXIN2, WNT10A, and EDA are proven candidate genes for familial tooth agenesis." (PMID 23227268, 2012). "Although studies have focused on the Msh homeobox 1 (MSX1) and paired box 9 (PAX9) genes in the etiology of non-syndromic hypodontia, it is believed that mutations in various gene families may contribute to this condition." (PMID 37865729, 2023). "In conclusion, the variants found in the PAX9, MSX1 and WNT10A genes may not play a role in nonsyndromic tooth agenesis, but further studies should be performed to explore the exact association between these SNPs and the disease." (PMID 33014315, 2020). "All variants were analyzed based on bioinformatics websites and Iranian gene databases, and as a result, it was revealed that variants of PAX9, MSX1 and WNT10A may not play a role in non-syndromic tooth agenesis among Iranian cases." (PMID 33014315, 2020). "However, among those 119 sequence variants a c.956G>T mutation in X-linked EDA1 was the unique one among six candidate genes (viz.PAX9, MSX1, AXIN2, WNT10A, EDAR and EDA1) associated with non-syndromic tooth agenesis known so far." (PMID 25203534, 2014).
Oligodontia (39 papers, 2008 to 2025). The absence of six or more teeth from the normal series by a failure to develop. "The EDARV370A genetic variant was associated with dental morphology among Uyghurs, and PAX9 and MSX1 gene mutations were related to non-syndromic oligodontia in Uyghurs." (PMID 40365427, 2025). "The asymmetrical tooth loss pattern and taurodont-like morphology were consistent with reports linking MSX1 mutations to variable expressivity in oligodontia." (PMID 40995403, 2025). "Heterozygous mutations in the MSX1 or PAX9 gene cause oligodontia; therefore, they share an autosomal dominant inheritance in humans." (PMID 38392624, 2024). "As previously seen monosomy of MSX1 was linked to the oligodontia observed in some WHS patients suggesting that selective tooth agenesis is a common phenotype in Wolf–Hirschhorn syndrome." (PMID 33627176, 2021). "In this study, we identified five novel MSX1 variants in Chinese families with oligodontia inherited in an autosomal-dominant manner: three missense variants (Q221P, R224C, and S270L), one nonsense variant (G122*), and one frameshift variant (A93Rfs*67)." (PMID 33419968, 2021). "It is in this non-coding region of exon 2 of the MSX1 gene that polymorphic variants, rs8670 and rs12532—which were originally correlated with non-syndromic, sporadic oligodontia in humans—were described for a Polish population." (PMID 33923458, 2021). "This study aimed to continue to expand the variant spectrum of MSX1 associated with nonsyndromic oligodontia, explore the functional impacts of the identified novel variant loci, and analyse the genotype–phenotype correlations." (PMID 33419968, 2021). "MSX1 gene mutations can lead to hypodontia or oligodontia as well as variations in the downstream signaling gene bone morphogenetic protein 4 (BMP4)." (PMID 33693441, 2020). "We demonstrated a novel MSX1 mutation causing familial nonsyndromic oligodontia and mechanically MSX1 regulates odontogenesis through the ERK signaling pathway in human dental pulp stem cells." (PMID 30134957, 2018). "We identified a novel frameshift mutation (c.128_147del20, p.Met43Serfsx125) of MSX1 in a Chinese family which manifested as autosomal dominant nonsyndromic oligodontia." (PMID 30134957, 2018). "Typically, the mutations in MSX1 gene are associated with oligodontia inherited in the autosomal dominant manner; to date only one case of autosomal recessive oligodontia has appeared." (PMID 30192788, 2018). "Genetic surveys of members of families with dominant autosomal oligodontia highlighted mutations in two transcription factors: Msh homeobox 1 (MSX1) in chromosome 4 (4p.16), and Paired box gene 9 (PAX9) in chromosome 14 (14q.21q.13)." (PMID 24716509, 2014). "Oligodontia is most commonly associated with several syndromes like ectodermal dysplasia, Down syndrome, and Van der Woude syndrome that involve the mutation of the MSX-1 and PAX-1 genes." (PMID 37378140, 2023). "The results indicated that G122*, A93Rfs*67, Q221P, and R224C severely affected the nuclear localization of MSX1, which might contribute to the pathogenic process of oligodontia in our patients." (PMID 33419968, 2021). "The two findings were also related to mutations in the MSX1 gene, which could help explain the moderate association between heart defects, micrognathia, and oligodontia detected in this study." (PMID 33158290, 2020). "Moreover, genetic mutations of PAX9 and MSX1 cause oligodontia, known as the developmental failure of ≥6 teeth." (PMID 30931425, 2019). "Of all these, MSX1, PAX9, EDA, and AXIN2 genes are most frequently associated with nonsyndromic hypodontia or oligodontia." (PMID 40995403, 2025). "Oligodontia can be caused by mutations in various genes involved in tooth development, like AXIN2, MSX1, and PAX9." (PMID 40136761, 2025).